NOS2 (nitric oxide synthase 2)
Diseases named in the same sentence as NOS2 in open-access papers (continued):
Sharing a sentence is not in itself a finding about the gene and the disease.
co-infection (4 papers, 2017 to 2022). "Remarkably, GAS application induced an approximately 3000-fold overexpression of Nos2 that was impeded during co-infection to a mere, yet statistically significant, 10-fold overexpression." (PMID 36365071, 2022). "The GAS-inducible upregulation of inflammatory genes, such as Nos2, as well as the secretion of TNFα and IL-1β were notably reduced or even abrogated following co-infection." (PMID 36365071, 2022). "Co-infected MLE12 cells had a higher concentration of nitric oxide than E. coli single-infected cells, suggesting that co-infection increases the expression of NOS2 in vitro." (PMID 33968006, 2021). "RNA sequencing further revealed that the expression of NOS2 was significantly elevated after virus-bacteria co-infection." (PMID 33968006, 2021). "Moreover, co-infection promoted bacterial growth by increasing nitric oxide synthase 2 (NOS2) expression." (PMID 33968006, 2021). "Importantly, nitric oxide synthase 2 (NOS2) expression was also significantly enhanced by the co-infection." (PMID 33968006, 2021). "We have previously shown that proinflammatory mediators (NOS2, IL-6, and TNF-α) increase in the heart of mice after co-infection with T. cruzi strains, and that fenofibrate is able to modulate this response." (PMID 33072115, 2020). "Moreover, SL3261 co-infection led to loss of the M(IL-4) activation phenotype in NeMΦ, as measured by intracellular Relm-α expression, but induction of NOS2 was independent of previous M(IL-4) activation as indicated by equivalent expression in Relm-α positive and negative cells." (PMID 28334040, 2017).
cognitive deficits (4 papers, 2020 to 2022). "Moreover, LDHB deficiency-induced gliosis increased the production of inflammatory mediators (TNF-α, Nf-ĸB, and NOS2), and revealed cognitive deficits." (PMID 35204143, 2022). "A total of 763 individuals (see Section 2.1.6 on “Cognitive Disorders” regarding NOS1, NOS2, andNOS3) were examined." (PMID 32111088, 2020). "LPS-treated mice had cognitive deficits; LPS administration to NOS2 KO mice did No change in the cognitive deficits." (PMID 35711904, 2022).
emphysema (4 papers, 2014 to 2024). "The absence of SP-D results in an inducible NO synthase (iNOS, coded by NOS2 gene) related chronic inflammation, development of emphysema-like pathophysiology and alterations of surfactant homeostasis." (PMID 24465666, 2014).
esophageal cancer (4 papers, 2011 to 2025). A primary or metastatic malignant neoplasm involving the esophagus. "Moreover, it was shown that due to increasing miR-155 expression by TAMs from esophageal cancer, the expression of IL-12, TNF-α, and Nos2 are enhanced, and tumor cells survive and migrate less in this condition." (PMID 34680504, 2021).
insulinoma (4 papers, 2014 to 2025). "Like insulinoma cells, IL-1β stimulated NOS2 expression in rat islets was attenuated in the presence of I-BET151." (PMID 36176467, 2022). "LPS also does not activate NF-κB in C57BL/6 islets as assessed by IκBα degradation 30 min after LPS stimulation, nor does it stimulate Nos2, Gbp2, or Gbp5 expression by rat insulinoma INS832/13 cells." (PMID 41093076, 2025).
liver fibrosis (4 papers, 2016 to 2022). "Genes encoding IL6, CRP and NOS2 were previously reported to exhibit dysregulation in liver fibrosis." (PMID 27135246, 2016). "An increase in nitric oxide synthase 2 (Nos2) expression is also positively related to the development of liver fibrosis." (PMID 35409415, 2022). "Our data on the effective reduction in M1 polarization markers NOS2, Il6, and TNF-α make siRNA to IRF5 a strong candidate for in vivo modulation of liver fibrosis." (PMID 36010574, 2022).
nasal polyp (4 papers, 2017 to 2024). "The expression of NOS2, NOX1, HO-1 and SOD2 was increased in nasal epithelial cells and macrophages derived from nasal polyp tissue." (PMID 38756779, 2024).
pancreatic ductal adenocarcinoma (4 papers, 2016 to 2023). An infiltrating adenocarcinoma that arises from the epithelial cells of the pancreas. "Similarly, elevated levels of NOS2 in pancreatic ductal adenocarcinoma were related to lower survival rates, and NOS2 deficiency in genetically engineered mice led to reduced proliferation, migration and invasion." (PMID 34200849, 2021). "NOS2 expression in PDAC (n = 147) was significantly higher than in normal pancreas (n = 171) (p < 0.0001), while the pancreatic ductal adenocarcinoma and skin cutaneous melanoma (n = 472) expressions were not significantly different." (PMID 27762323, 2016).
pancreatitis (4 papers, 2005 to 2020). Inflammation of the pancreas. "It is noteworthy that the PGC-1α levels lowered in the obese mice livers, which increased the Nos2 mRNA expression and protein nitration levels and decreased energy charge during pancreatitis." (PMID 32961723, 2020). "This pro-oxidant environment in the livers of the PGC-1α KO mice, together with specific Nos2 induction, would explain the more marked nitration pattern observed in the livers of these mice with pancreatitis." (PMID 32961723, 2020). "According to our results, Nos2 transcription in the liver during pancreatitis seems to depend on PGC-1α levels." (PMID 32961723, 2020). "By taking into account our previous studies, in which the plasma levels of IL-6 increased in the PGC-1α KO mice with pancreatitis, we considered studying whether NF-κB and STAT3 activation are involved in inducing Nos2 in the liver upon PGC-1α deficiency." (PMID 32961723, 2020). "Consequently, we observed higher Nos2 gene expression and protein nitration levels and decreased energy charge in the livers of obese mice compared to the lean mice with pancreatitis." (PMID 32961723, 2020). "Remarkably, and consistently with the increased Nos2 mRNA expression observed in the livers of the PGC-1α KO mice with pancreatitis, we detected higher levels of 3-nitrotyrosine, a marker of protein nitration measured by mass spectrometry, in the livers of these mice compared to the other groups." (PMID 32961723, 2020). "The increased transcript Nos2 levels and the pro-oxidant liver status caused by the down-regulated expression of the PGC-1α-dependent antioxidant genes enhanced nitrosative stress and decreased energy charge in the livers of the PGC-1α KO mice with pancreatitis." (PMID 32961723, 2020). "Nevertheless, we did not note any increase in the protein nitration levels in the liver after inducing pancreatitis, which is consistent with the PGC-1α-dependent repression of Nos2 in this tissue." (PMID 32961723, 2020). "We also observed a marked increase in the binding of p65 to p-STAT3 in the obese mice with pancreatitis, which supports the notion that lack of PGC-1α in obese mice livers may be associated with inducing Nos2 during AP." (PMID 32961723, 2020). "Similarly, the Western blot also showed NOS2 induction during AP, although there was no change between WT and KO mice with pancreatitis." (PMID 32961723, 2020).
peritonitis (4 papers, 2012 to 2025). Inflammation of the peritoneum (tissue that lines the abdominal wall and covers most of the organs in the abdomen). "On the other hand, oxidative/nitrosative stress linked to NOS-2 expression was shown to contribute to lung injury, while all nitric oxide synthase isoforms contribute to acute peritonitis, showing evidence of organ- and time-dependent ∙NO-dependent protection." (PMID 31249650, 2019). "In the present study, the GG genotype of NOS2 rs2297518 polymorphism (p.Ser608Leu), located in exon 16, initially showed a significant association with an increased risk of developing ARDS and MODS in patients with secondary peritonitis." (PMID 41226345, 2025). "CDC-EVs enhance the Arg1/Nos2 ratio in macrophages in vitro and reduce MI size more than MSC-EVs and suppress inflammation during acute peritonitis in vivo." (PMID 33883598, 2021).
schizophrenia (4 papers, 2011 to 2022). A major psychotic disorder characterized by abnormalities in the perception or expression of reality. "This was done with the genes’ expression analysis in brain tissue, using Nos1, Nos2, Nos3, Plcg1, Prkcg, Ptgs2, and Ptk2, all associated with schizophrenia presentation." (PMID 35884767, 2022). "An apparent close connection between the ketamine and BPC 157 was noted in the genes’ expression analysis in brain tissue, using Nos1, Nos2, Nos3, Plcg1, Prkcg, Ptgs2, and Ptk2 all associated with schizophrenia presentation." (PMID 35884767, 2022).
allergic asthma (3 papers, 2011 to 2021). A asthma with a basis in a pathological type I hypersensitivity reaction. "However, further functional studies are required to elucidate if this variant affects NOS2 translation and thus may represent of novel risk factor in the allergic asthma." (PMID 34946286, 2021). "Increased expression of arginase I and NOS2 occurs in murine models of allergic asthma and in biopsies of asthmatic airways." (PMID 23554705, 2011). "The demonstration that NOS2 produces peroxynitrite in allergic asthma indicates that NOS2 already tends to produce superoxide rather than nitric oxide under this condition." (PMID 29792217, 2018).
amyloidosis (3 papers, 2020 to 2023). A disorder characterized by the localized or diffuse accumulation of amyloid protein in various anatomic sites. "We have also confirmed the effects of knocking out Nos2 on tau pathology, by crossing another amyloid model, Tg2576 (APPSw), with Nos2 knock-out mice." (PMID 37650081, 2023). "Conversely, another study using the CVN-AD mouse model (Nos2 null) showed that sustained elevated extracellular Arg1 level stimulated amyloidosis and promoted hippocampal neuronal death." (PMID 34046031, 2021). "Probably, Arg1 and NOS2 activities, their respective byproducts, and arginine depletion/repletion are temporally critical regarding microglial response to amyloidosis." (PMID 33519806, 2020).
anemia (3 papers, 2012 to 2018). A reduction in the number of red blood cells, the amount of hemoglobin, and/or the volume of packed red blood cells. "Besides, several targets such as CA2, HMOX1, GSTA1, and NOS2 were closely associated with anemia, which could exhibit significant influences on the therapeutic effects of XSHG." (PMID 29551975, 2018). "Even so, a number of marginal susceptibility genotype associations were also observed between specific gene mutations and anaemia (GBP7), CM (CD40LG), hyperparasitaemia (NOS2), hyperpyrexia (CD36, CD40LG, G6PD), SMA (EMR1) and UM (NOS2, EMR1)." (PMID 24934404, 2014).
autoimmune disease (3 papers, 2016 to 2025). A disorder resulting from loss of function or tissue destruction of an organ or multiple organs, arising from humoral or cellular immune responses of the individual to their own tissue constituents. "Increased activity of NOS2 and activation of HIFs are important features of acute and chronic inflammation in autoimmune diseases." (PMID 37373923, 2023). "NOS2’s capacity of regulating the activation and induction of HIFs and NO-mediated hypoxia are important elements in chronic inflammatory disorders and in autoimmune diseases." (PMID 37373923, 2023).
Barrett esophagus (3 papers, 2017 to 2021). Esophageal lesion lined with columnar metaplastic epithelium which is flat or villiform. "In Barrett’s esophagus and related adenocarcinoma, expression of inducible nitric oxide synthase (NOS-2) is increased, and NOS-2 also plays a role in inflammation and epithelial cell growth." (PMID 33541291, 2021).
brain injury (3 papers, 2017 to 2023). Acute and chronic (see also brain INJURIES, CHRONIC) injuries to the brain, including the cerebral hemispheres, CEREBELLUM, and brain STEM. "NOS-2 and NOX-2 are implicated in oxidative damage of subarachnoid hemorrhagic brain injury." (PMID 28912935, 2017).
Chagas disease (3 papers, 2018 to 2024). A parasitic infection caused by Trypanosoma cruzi. "During experimental Chagas disease, LRG-47- and NOS2-dependent effector mechanisms in CAM are crucial to eliminate T. cruzi." (PMID 30555475, 2018). "Taken together, IL-13 overexpression did not negatively affect the generation of NOS2-dependent effector responses in CAM, the pro-inflammatory cytokine release and inflammation during experimental Chagas disease." (PMID 30555475, 2018).
Cirrhosis (3 papers, 2013 to 2025). A chronic disorder of the liver in which liver tissue becomes scarred and is partially replaced by regenerative nodules and fibrotic tissue resulting in loss of liver function. "Nitric oxide synthase 2, the product of Nos2 gene, is involved in triggering systemic vascular responses associated with fibrotic and cirrhosis processes and also with regeneration." (PMID 23874726, 2013). "Furthermore, HCV and HBV induced nitric oxide overproduction (that is confined to NOS2) in hepatocytes is involved in progression of chronic viral hepatitis to cirrhosis." (PMID 27135246, 2016). "Among all, the top 5 hub genes identified for NAFLD vs. control were CXCL9, NOS2, SERPINE1, FABP4, and LPL, whereas AKR1D1, UGT2B17, CYP26B1, LIPC, and DGAT2 were identified as the top 5 hub genes for the NAFLD vs. cirrhosis group." (PMID 40365443, 2025). "Additionally, the top 5 biological functional hub genes in NAFLD vs. control (CXCL9, NOS2, SERPINE1, FABP4, and LPL) and NAFLD vs. cirrhosis (AKR1D1, UGT2B17, CYP26B1, LIPC, and DGAT2) groups were identified through PPI analysis among lipid, immune, and metabolism dysregulated genes." (PMID 40365443, 2025).
colon adenocarcinoma (3 papers, 2014 to 2023). "We next tested the ability of SLAB51 to inhibit NOS2 activity, using the human colon adenocarcinoma-derived CaCo-2 cells, which constitutively express high levels of NOS2 as shown by the RT-PCR analysis, thus confirming previous reports." (PMID 34445055, 2021).
diabetic nephropathy (3 papers, 2013 to 2024). "Lower NOS1 and NOS2 concentrations were observed in the diabetic nephropathy group compared to the control group (p = 0.002, p < 0.001, respectively)." (PMID 39061907, 2024). "The logistic regression was used to assess the risk of developing diabetic nephropathy or the likelihood of renal replacement therapy based on NOS1, NOS2, and NOS3 polymorphisms." (PMID 39061907, 2024). "The aim of this study was to assess the role of selected NOS polymorphisms—rs3782218 (NOS1), rs1137933 (NOS2), rs1799983, rs2070744, and rs61722009 (NOS3)—in the risk of developing diabetic nephropathy and in the likelihood of renal replacement therapy." (PMID 39061907, 2024). "The aim of this study was to assess the frequency of selected polymorphisms of genes encoding all three NOS isoforms—NOS1, NOS2, and NOS3—in patients with diabetic nephropathy, both after and without kidney transplantation." (PMID 39061907, 2024).
diabetic neuropathy (3 papers, 2016 to 2024). A chronic, pathological complication associated with diabetes mellitus, where nerve damages are incurred due to diabetic microvascular injury involving small blood vessels that supply these nerves, resulting in peripheral and/or autonomic nerve dysfunction. "Nitric oxide produced by the inducible nitric oxide synthase (NOS2) has been implicated in diabetic neuropathy as demonstrated by the reduced allodynia observed in diabetic NOS2 deficient mice." (PMID 26730587, 2016). "In conclusion, our data provide the first evidence that the induction of HO-1 attenuated STZ-induced painful diabetic neuropathy and enhanced the antinociceptive effects of morphine via inhibition of microglia activation and NOS2 overexpression as well as by increasing the spinal cord levels of MOR." (PMID 26730587, 2016). "In conclusion, our results demonstrated that the induction of HO-1 might alleviate diabetic neuropathy and enhanced the antinociceptive effects of morphine via inhibition of microglia activation and NOS2 overexpression as well as by regulating MOR spinal cord expression." (PMID 26730587, 2016). "However, whether HO-1 induction might avoid spinal microglial activation and reduces the liberation of inflammatory mediators, such us nitric oxide synthetized by NOS2 in diabetic neuropathy, remained to be investigated." (PMID 26730587, 2016). "Therefore, the reduced protein levels of NOS2 observed in the spinal cord from diabetic mice treated with CoPP suggests that the alleviation of diabetic neuropathy produced by this HO-1 inducer compound might be also due by blocking the spinal synthesis of nitric oxide produced by NOS2." (PMID 26730587, 2016).
dyslipidemia (3 papers, 2019 to 2022). "Furthermore, a positive selection for nitric oxide synthase 2 (NOS2A) has been described in Andeans, even though this pattern cannot fully explain discrepancies in body weight composition and dyslipidemia observed in this population." (PMID 31212599, 2019).
E. coli infection (3 papers, 2023 to 2025). "Interestingly, NOS2 mRNA was downregulated in SC-236 treated 5637 cells and remained reduced after E. coli infection both on mRNA and protein levels." (PMID 37697284, 2023). "Interestingly, NOS2 mRNA was upregulated in LD4-PP-treated uroepithelial cells when treated with LD4-PP, but when treated after E. coli infection, the effect was outcompeted." (PMID 41415272, 2025). "E. coli infection further increased the expression of NOS2, whereas in LD4-PP treated cells, we observed no marked change in the expression of NOS2 levels at the protein level." (PMID 41415272, 2025).
falciparum malaria (3 papers, 2013 to 2016). "Compared to control children (n = 106), children with moderately severe (n = 77) and severe falciparum malaria (n = 129) had significantly higher mononuclear cell arginase 1 mRNA, protein, and enzyme activity; lower NOS2 mRNA; lower plasma arginine; and higher plasma IL-10, IL-13, and IL-4." (PMID 27385484, 2016). "We note that Tanzanian children with falciparum malaria have markedly increased PBMC arginase 1 and IL-10, reduced PBMC NOS2 and plasma arginine, and monocytes expressing markers of alternative activation (M2-like monocytes)." (PMID 27385484, 2016). "We show here that children with falciparum malaria have significantly increased levels of PBMC arginase 1 mRNA and protein, elevated plasma arginase activity, decreased PBMC NOS2 mRNA, and dramatically increased plasma levels of IL-10." (PMID 27385484, 2016). "Since M2 cells express very low NOS2/NO and produce high levels of arginase 1, an enzyme that depletes the NOS substrate arginine, we sought to characterize monocytes from children with falciparum malaria." (PMID 27385484, 2016).
gastric tumors (3 papers, 2020 to 2023). "Gastric tumors had upregulated NOS2 and downregulated ASL, PRMT2, ORNT1, and DDAH1 expression." (PMID 34439753, 2021). "The expression of Ki67 and NOS2 was independently associated with CLDN2 in non-cancerous adjacent tissue, explaining 83% in its variation, and BCLxL was independently associated with CLDN2 in gastric tumors, explaining 64% in its variability." (PMID 32630408, 2020).
gastritis (3 papers, 2010 to 2021). Inflammation of the stomach. "When there are gastric injuries caused by H. pylori infection, the iNOS enzyme can play an important role in carcinogenesis, once the gastritis can persist for years and NOS2 stays active during all the process." (PMID 20565800, 2010). "PTGS2, NOS2, EGFR, MMP9, CXCL2, CXCL8, and IL-10 may be the important direct targets of Weibing Formula 1 in gastritis treatment." (PMID 34471638, 2021). "The analysis of the gene expression of ARG1, ARG2, and NOS2 was performed in the patients with chronic active gastritis, chronic inactive gastritis, no gastritis, or the control group." (PMID 31320834, 2019). "In conclusion, the potential mechanism of Weibing Formula 1 in treating gastritis has the multicomponent, multitarget, and multiway characteristics, and PTGS2, NOS2, EGFR, MMP9, CXCL2, CXCL8, and IL-10 may be the important direct targets of Weibing Formula 1 in gastritis treatment." (PMID 34471638, 2021).